EFNB2 (ephrin B2)
Diseases named in the same sentence as EFNB2 in open-access papers (continued):
Sharing a sentence is not in itself a finding about the gene and the disease.
hypospadias (4 papers, 2011 to 2025). Hypospadias is the displacement of the urethral meatus on the ventrum of the penis. "Exposure to estrogen during later stages of urethra internalization could cause a mild reduction in Leat1 and subsequently EfnB2 expression, resulting in mild distal forms of hypospadias." (PMID 37461443, 2023). "Moreover, the loss of Leat1 leads to reduced EfnB2, resulting in a severe hypospadias phenotype." (PMID 37461443, 2023). "We examined LEAT1 and EFNB2 mRNA levels in the transcriptomes of urethral plate epithelium (UPE) isolated from patients undergoing repair surgery for mild hypospadias between 6 months and 16 months post-partum." (PMID 41398470, 2025). "We examined LEAT1 and EFNB2 mRNA levels in the transcriptomes of urethral plate epithelium (UPE) isolated from patients undergoing repair surgery for mild hypospadias." (PMID 37461443, 2023). "Exposure to exogenous estrogen during this developmental window can reduce Leat1 expression, leading to inhibition of EfnB2 mRNA below required levels resulting in hypospadias." (PMID 37461443, 2023). "Deletion of Leat1 leads to a suppression in EfnB2 expression and a complete lack of urethral closure resulting in hypospadias." (PMID 37461443, 2023).
lung fibrosis (4 papers, 2019 to 2024). "Ephrin-B2 and its receptors EphB3 and EphB4 can promote fibrosis of multiple organs and blockade of Ephrin-B2 signaling ameliorates or prevents cardiac and lung fibrosis in mice." (PMID 39164267, 2024). "In a separate model of lung fibrosis, cleavage of the ligand ephrin-B2 on fibroblasts by the disintegrin and metalloproteinase domain-containing protein ADAM10 leads to increased fibroblast activation and subsequently increased skin and lung fibrosis." (PMID 31333644, 2019). "Interestingly, ADAM10-mediated proteolytic shedding of ephrin-B2 promoted fibroblast recruitment and activation as well as lung fibrosis." (PMID 35280996, 2022).
osteoporosis (4 papers, 2020 to 2022). A condition of reduced bone mass, with decreased cortical thickness and a decrease in the number and size of the trabeculae of cancellous bone (but normal chemical composition), resulting in increased fracture incidence. "The glucocorticoid-induced osteoporosis mouse model causes down-regulation of EphB4 in osteoblasts and up-regulation of ephrin-B2 in osteoclasts." (PMID 33634116, 2021). "EphB4-ephrin-B2 expression is also dysregulated in a diabetes-related osteoporosis model." (PMID 33634116, 2021).
rhabdomyosarcoma (4 papers, 2017 to 2024). A rare aggressive malignant mesenchymal neoplasm arising from skeletal muscle. "An increased expression of EPHs (EPHB1, EPHB2, EPHB3, and EPHB4) and their ephrin ligands (ephrin-B1 and ephrin-B2) has been implicated in promoting angiogenesis and tumor progression in rhabdomyosarcoma." (PMID 38612645, 2024).
viral infection (4 papers, 2010 to 2025). "EFNB1 and its homologs EFNB2 and EFNB3 have previously been implicated in viral infections as receptors for henipaviruses, including Nipah, Hendra and Cedar viruses." (PMID 41332748, 2025). "In competition assays, the infection of the pseudotypes could also be specifically blocked using recombinant, soluble ephrin-B2 or ephrin-B3 receptor proteins as was previously shown with both henipavirus-mediated membrane fusion as well as live virus infection assays." (PMID 21073718, 2010). "A subset of genes including OAS1, OAS2, EFNB2, and CKS1B involved in the immune response to viral infection showed a higher expression level and H3K4me3 enrichment in PEDV-infected samples, suggesting the role of H3K4me3 deposition in promoting their expression." (PMID 31382472, 2019).
Cerebral ischemia (3 papers, 2018 to 2019). Restriction of arterial blood supply to the brain associated with insufficient oxygenation to support the metabolic requirements of the tissue. "Moreover, ephrin-B2/EphB4 signaling has been shown to be involved in the restoration of the BBB and neurovascular repair mechanisms upon cerebral ischemia, underlining the importance of ephrin/Eph communication at the neurovascular interface for cellular responses to stroke." (PMID 30722785, 2019). "We investigated the therapeutic potential of peripheral blood-derived mononuclear cells (PB-MNC) harvested from diabetic patients and stimulated by ephrin-B2 (PB-MNC+) (500,000 cells), injected intravenously 18–24 hours after induced cerebral ischemia in mice." (PMID 29736174, 2018). "We speculated that PB-MNC from type-2 diabetic patients, stimulated by ephrin-B2 (PB-MNC+) and transplanted into mice 18–24 hours after induction of experimental cerebral ischemia, would be more effective than PBS or unstimulated PB-MNC in promoting stroke recovery." (PMID 29736174, 2018).
head and neck cancer (3 papers, 2022 to 2024). A primary or metastatic malignant neoplasm affecting the head and neck. "A recent study showed that blocking EFNB2/EPHB4 signaling increased the response to cetuximab-radiation therapy in head and neck cancers." (PMID 36376513, 2023).
Hypertension (3 papers, 2017 to 2021). The presence of chronic increased pressure in the systemic arterial system. "We have found that five single nucleotide polymorphisms (SNPs) in the 3′ region of EFNB2 gene are significantly associated with hypertension for male but not female patients with type 2 diabetes, and the coding (minor) allele of these SNPs are protective against hypertension in male Caucasians28." (PMID 30262919, 2018). "The deletion of EPHB6, EFNB1 and EFNB3 all result in hypertension in mice, while the deletion of EFNB2 leads to an opposite phenotype, i. e., hypotension." (PMID 30262919, 2018). "Also, several studies have shown the association of this gene hypertension and type 2 diabetes; however, there have been no reports regarding the connection of EFNB2 with obesity-related traits." (PMID 33654129, 2021).
lymph node metastases (3 papers, 2011 to 2024). "The results revealed positive correlations between EFNB2 expression and the number of lymph node metastases and stage of the disease." (PMID 39839790, 2024). "In this study, we found a correlation between ephrin-B2 expression level and lymph node metastasis in biopsy specimens of primary lesions." (PMID 29190834, 2017). "EFNB2 overexpression is reported to be significantly correlated with the number of lymph node metastases and clinical stage in esophageal cancer." (PMID 21333016, 2011). "Furthermore, we found that ephrin-B2 immunoreactivity was significantly correlated with lymph node metastasis (p < 0.001) and clinical stage (p = 0.003)." (PMID 29190834, 2017). "Thus, ephrin-B2-targeted therapy might be useful as a prophylactic treatment for lymph node metastasis of OSCC, and if proven effective, in combination with primary treatment." (PMID 29190834, 2017).
metastatic disease (3 papers, 2022 to 2025). "Finally, we identified the EPHs (EPHA2, EPHA4, EPHA8, and EPHB4) and EFNs (EFNA1, EFNA3, EFNA4, and EFNB2) that are significantly overexpressed in the aggressive epithelioid histological subtype and revealed that the majority of EPHs/EFNs are overexpressed in metastatic disease." (PMID 41516312, 2025).
neuropathic pain (3 papers, 2008 to 2012). Chronic pain caused by damage to nerve fibers. "The present studies demonstrate that presynaptic ephrin-B2 expressed by Nav1.8+ nociceptors has an important role in regulating to the central nervous system in conditions of inflammatory and neuropathic pain." (PMID 21059214, 2010).
osteoarthritis (3 papers, 2016 to 2024). A noninflammatory degenerative joint disease occurring chiefly in older persons, characterized by degeneration of the articular cartilage, hypertrophy of bone at the margins and changes in the synovial membrane. "We have demonstrated that ephrin-B2 (EFNB2) could play a role in knee joint pathology associated with osteoarthritis (OA)." (PMID 26980243, 2016).
schizophrenia (3 papers, 2012 to 2021). A major psychotic disorder characterized by abnormalities in the perception or expression of reality. "EFNB2 has been reported to be associated with schizophrenia and ankle injury through the genome-wide association study." (PMID 33654129, 2021). "Multiple genes encoded by chromosome 13 have been suggested to contribute to schizophrenia susceptibility, including DAOA, 5-HTR2A, KPNA3 and KPNB3, ESD, ATXN8OS, KFL5, EFNB2, and PCDH8." (PMID 22214315, 2012).
squamous cell carcinoma (3 papers, 2011 to 2021). A carcinoma arising from squamous epithelial cells. "However, it has been reported that Ephrin B2 promotes squamous cell carcinoma as well targeting MMD1 and MMP13." (PMID 31065284, 2019). "Compared with adenocarcinoma, squamous cell carcinoma showed strong communications with endothelial by the MIF/TNFRSF10D, EGFR/GRN, EGFR/HBEGF, and EPHB2/EFNB2 interactions." (PMID 34185421, 2021).
Stroke (3 papers, 2018 to 2022). Sudden impairment of blood flow to a part of the brain due to occlusion or rupture of an artery to the brain. "Finally, we showed in our present study that mononuclear cells from peripheral blood of diabetic patients, and stimulated by ephrin-B2, are capable to enhance neurorepair in stroke." (PMID 29736174, 2018). "We therefore set out to evaluate the therapeutic potential of PB-MNC isolated from diabetic patients (a population at risk for stroke) and stimulated (PB-MNC+) or not by ephrin-B2, administered intravenously into healthy, nondiabetic, adult male C57Bl6J mice subjected to focal cerebral ischemia." (PMID 29736174, 2018).
bladder cancer (2 papers, 2014 to 2017). "Moreover, CSTF2, POLA1, HMOX2, and EFNB2 may be associated with the prognosis of bladder cancer patient." (PMID 28320388, 2017). "However, HMOX2 and EFNB2 may be the risk factors of bladder cancer." (PMID 28320388, 2017). "All of these results might indicate that CSTF2 and EFNB2 were two important protective factors in the prognosis of bladder cancer." (PMID 28320388, 2017). "HMOX2 (heme oxygenase-2), CSTF2 (cleavage stimulation factor, 3′ pre-RNA, subunit 2, 64 kDa), and POLA1 (polymerase (DNA directed), alpha 1) were the three obviously significant related genes, and a marginal significant correlation was found between EFNB2 (ephrin-B2) and prognosis of bladder cancer." (PMID 28320388, 2017).
cervical cancer (2 papers, 2021 to 2023). A primary or metastatic malignant neoplasm involving the cervix. "In ovarian, endometrial and cervical cancers, sfTSLP is mainly expressed and promotes tumour growth probably via the downregulation of the Ephrin-B2 (EFNB2) protein." (PMID 37628907, 2023). "Likewise, EPHB4 and ephrin-B2 expression were reported higher in cervical cancer and Cervical Intraepithelial Neoplasia specimens and associated with tumor diameter, with EPHB4 additionally associated with disease stage." (PMID 34445116, 2021).
coronary artery disease (2 papers, 2011 to 2024). "An example is two Ephrin receptors (EFNB2 Ephrin-B2 and EPHA7 EPH receptor A7) which Gentrepid predicted as candidates for coronary artery disease in the adjacent gene set." (PMID 22077927, 2011).
esophageal cancer (2 papers, 2011 to 2012). A primary or metastatic malignant neoplasm involving the esophagus. "Ephrin-B2 has also shown to be upregulated in many cancers, including colon, uterine, ovarian and esophageal cancers." (PMID 22292016, 2012).
experimental autoimmune encephalomyelitis (2 papers, 2021 to 2024). An autoimmune demyelinating disease of the central nervous system that is produced experimentally in animals by the injection of homogenized brain or spinal cord in Freund's adjuvant. "In experimental autoimmune encephalomyelitis and multiple sclerosis, the expression of EFNB1 and EFNB2 was found to be related to the migration of T cells." (PMID 35126464, 2021).
ischemic stroke (2 papers, 2019 to 2022). A stroke disorder caused by obstruction of blood flow to the brain, due to thrombotic (local blood clot formation) or embolic (due to a blood clot or other material traveling from another site) event. "Moreover, brain-specific loss of ephrin-B2 in mice reduced the extent of cerebral tissue damage in the acute phase of ischemic stroke." (PMID 30722785, 2019). "Furthermore, neuron-specific loss of ephrin-B2 reduced the extent of cerebral tissue damage in the acute phase of ischemic stroke." (PMID 30722785, 2019). "Overall, our experimental data strongly suggest that glutamate-induced excitotoxic neuronal damage and inflammation during early acute ischemic stroke is substantially enhanced by EphB2/ephrin-B2 forward and reverse signaling in neurons and astrocytes, respectively." (PMID 30722785, 2019).
liver cancer (2 papers, 2018 to 2023). An epithelial or non-epithelial malignant neoplasm that arises from the liver. "It indicated that EFNB2 was overexpressed in human liver cancer, and the overexpression was correlated with tumour progression and poor patient outcome." (PMID 30589500, 2018). "To investigate the clinical significance of EFNB2 in liver cancer, we firstly analysed the EFNB2 gene in the TCGA database to examine the correlation of EFNB2 with normal and clinical liver tissues." (PMID 30589500, 2018). "EFNB2 was significantly highly expressed in liver cancer tissues than in normal tissues." (PMID 30589500, 2018).
medulloblastoma (2 papers, 2018 to 2024). A malignant, invasive embryonal neoplasm arising from the cerebellum. "Ephrin-B2 has been reported to be expressed in all medulloblastoma tumors, while ephrin-B1, associated with more aggressive phenotypes, was expressed in 20% of the tumors." (PMID 38612645, 2024). "While ephrin-B1 is uniquely dysregulated in medulloblastoma, differential effects of ephrin-B1 and ephrin-B2 knockdown on phosphorylation of EphB1/B2 and Src suggest alterations in reverse signaling in medulloblastoma cells." (PMID 29682554, 2018).
renal fibrosis (2 papers, 2023 to 2025). A final common manifestation of a wide variety of chronic kidney diseases characterized by glomerulosclerosis and tubulointerstitial fibrosis. "Ephrin-B2 knockout mice are protected from renal fibrosis in a renal ischemia model, suggesting that ephrin-B2 facilitates renal fibrosis." (PMID 37816758, 2023).
small cell lung carcinoma (2 papers, 2008 to 2021). Small cell lung cancer (SCLC) is a highly aggressive malignant neoplasm, accounting for 10-15% of lung cancer cases, characterized byrapid growth, and early metastasis. "EPHB2, as an EPHB subgroup receptor kinase, could modulate the biological behavior of small cell lung carcinoma through autocrine and/or juxtracrine activation by ephrin-B ligands (EFNB1, EFNB2, and EFNB3) that are expressed in the same or neighboring cells." (PMID 34645436, 2021).
abdominal aortic aneurysm (1 paper, 2025). Enlargement and ballooning of the vessel that supplies arterial blood to the abdomen, pelvis and legs. "The downregulation of Ephrin receptor tyrosine kinases, particularly ephrin-B2, impacts the progression and potential rupture of abdominal aortic aneurysms (AAA) through several mechanisms." (PMID 40507607, 2025).
aneurysm (1 paper, 2025). Bulging or ballooning in an area of an artery secondary to arterial wall weakening. "Altered ephrin-B2 signaling can lead to increased endothelial permeability and pro-inflammatory differentiation, exacerbating vascular inflammation and promoting aneurysm growth." (PMID 40507607, 2025). "Disruption of ephrin-B2 signaling can lead to impaired endothelial cell behavior, contributing to vascular instability and aneurysm development." (PMID 40507607, 2025).
anorectal malformation (1 paper, 2017). "In previous cytogenetic studies, two large 13q de novo deletions (9 Mb and 28 Mb in size) involving both ARGLU1 and EFNB2 were reported in patients with mild anorectal malformations and EFNB2 was proposed as a good candidate disease gene." (PMID 28934986, 2017).
Anxiety (1 paper, 2021). Intense feelings of nervousness, tension, or panic often arise in response to interpersonal stresses. "This is the first study to identify the fear- and anxiety-associated genes through WGCNA in Efnb2 knockout mice." (PMID 34281570, 2021). "To investigate whether the loss of Efnb2 in PV+ affects anxiety, we examined the behavior of wild type and Efnb2 in PV+ neurons knockout (KO) mice." (PMID 34281570, 2021). "To investigate whether genetic Efnb2 variants affect fear and anxiety behaviors, we tested the behavior of mice using the experiments of marble burying, cold stress defecation, and elevated plus maze (EPM) between wild-type (WT) and knock-out (KO) mice." (PMID 34281570, 2021). "We confirmed that Efnb2 on PV+ neurons are important components of fear and anxiety behaviors, which suggested that the identification of the module associated with the fear and anxiety behaviors can provide a treatment strategy and therapeutic target to regulate fear and anxiety symptoms." (PMID 34281570, 2021). "Together with the transcriptomic analysis of mice with Efnb2 knockout on PV+ neurons, our findings suggest that Efnb2 gene in the PV+ neuron of PFC may be a crucial factor for fear and anxiety, which provide an insight into anxiety pathophysiology." (PMID 34281570, 2021). "We showed that Efnb2 gene in PV+ neurons of PFC could affect fear and anxiety." (PMID 34281570, 2021).
coronary artery aneurysm (1 paper, 2023). "Our research focuses on the therapeutic effect of EFNB2-Fc in protecting endothelial cells and preventing coronary aneurysms." (PMID 37111257, 2023).
esophageal squamous cell carcinoma (1 paper, 2017). Esophageal squamous cell carcinoma (ESCC) is a type of esophageal carcinoma (EC) that can affect any part of the esophagus, but is usually located in the upper or middle third. "EFNB2 has been evidenced to be the prognostic maker for esophageal squamous cell carcinoma." (PMID 28320388, 2017).
Hyperglycaemia (1 paper, 2020). "Hyperglycaemia-activated miR-503 is packaged into endothelial EVs and delivered to vascular pericytes, resulting in reduced expression of Ephrin-B2 (EFNB2) and vascular endothelial growth factor (VEGF) in these cells, followed by impaired migration and proliferation." (PMID 32821437, 2020).
insulinomas (1 paper, 2010). "Furthermore, the simultaneous suppression of Dll4/Notch and Ephrin-B2/EphB4 signaling in sEphB4-Alb treated RT2 Dll4+/- mice drastically reduced the vessel diameters and their mural cell coverage, even though the total PECAM-positive area apparently similar to PBS-treated Dll4+/+ insulinomas." (PMID 21092311, 2010).
ischemia (1 paper, 2019). A hypoperfusion of the BLOOD through an organ or tissue caused by a PATHOLOGIC CONSTRICTION or obstruction of its BLOOD VESSELS, or an absence of BLOOD CIRCULATION. "The early phosphorylation of EphB2 after the onset of ischemia, prompted us finally to have a closer look at its ligand ephrin-B2." (PMID 30722785, 2019).
Kaposi's sarcoma (1 paper, 2014). A malignant neoplasm characterized by a vascular proliferation which usually contains blunt endothelial cells. "In Kaposi sarcoma, KSHV-mediated upregulation of EZH2 was required for the induction of Ephrin-B2, an essential pro-angiogenic factor which drove endothelial cell tube formation." (PMID 25237831, 2014).
measles (1 paper, 2023). A highly contagious viral infection caused by the measles virus. "EFNB2 is a receptor for Hendra and Nipah virus, CD4 for human immunodeficiency virus, CXADR is the coxsackievirus and adenovirus receptor, and BSG has been shown to be involved in infection of measles and human cytomegalovirus." (PMID 38140653, 2023).
mental disorder (1 paper, 2021). A disease that has its basis in the disruption of mental process. "Whether the Efnb2 gene on PV+ neurons can regulate the mental disorder has not been studied." (PMID 34281570, 2021).